SASH1 (SAM and SH3 domain containing 1)
Diseases named in the same sentence as SASH1 in open-access papers (continued):
Sharing a sentence is not in itself a finding about the gene and the disease.
preeclampsia (continued). "SASH1 protein was expressed in the cytoplasm and nucleus of the placental trophoblast cells, suggesting that SASH1 gene might play a role in abnormal placental development in preeclampsia patients." (PMID 33134379, 2020). "We identified characteristic genes of preeclampsia as LEP, FLT1, RAB6C, and SASH1 using the GEO database and verified them using the GSE160888 and GSE96985 datasets." (PMID 37389124, 2023). "Therefore, it is reasonable to hypothesize that SASH1 gene might play a part in abnormal placental development in preeclampsia and the upregulation of SASH1 protein might be related to inadequate trophoblast cell invasion in the placental tissues of preeclampsia patients." (PMID 33134379, 2020). "Therefore, it is possible that elevated expression of SASH1 during the development of placenta could potentially affect trophoblast migration and invasion, leading to shallow trophoblast cell invasion and poor arteriole remodeling in the placental tissues of preeclampsia patients." (PMID 33134379, 2020). "However, the protein expression level and the specific role of SASH1 in preeclampsia have not yet been reported." (PMID 33134379, 2020).
rotator cuff tears (3 papers, 2019 to 2022). "Moreover, two SNPs, residing in SAP30BP on chromosome 17 and SASH1 on chromosome 6, implicated in the cellular process of apoptosis, were significantly associated with rotator cuff tears." (PMID 32303186, 2020).
atherosclerosis (2 papers, 2010 to 2017). A disease characterized by the build-up of fatty material and calcium deposition in the arterial wall resulting in partial or complete occlusion of the arterial lumen. "SASH 1 (SAM and SH3 domain containing 1) expression levels have also been associated with smoking and smoking-related atherosclerosis." (PMID 28193179, 2017). "The fact that PTGDS and SASH1 expression remained associated with carotid plaques after adjustment on smoking status may indicate a broader implication of these genes in atherosclerosis than the sole effect induced by smoking." (PMID 20502693, 2010).
Bladder Cancer (2 papers, 2023). "MiR-130b also inhibits tumor suppressor function in esophageal squamous cell carcinoma by repression of PTEN and SASH1, and in bladder cancer by targeting VGLL4." (PMID 36701370, 2023).
ichthyosis (2 papers, 2021 to 2022). Disorders of cornification that are characterized by visible scaling and/or hyperkeratosis of most or all of the skin. "Patients suffering from specific inherited forms of PPK (i.e. Huriez syndrome, Olmsted syndrome, a subset of patients suffering from keratitis-ichthyosis-deafness, hereditary dyschromatosis that is due to mutations in SASH1 gene) are prone to SCC development." (PMID 35854363, 2022).
lung adenocarcinoma (2 papers, 2020 to 2025). A carcinoma that arises from the lung and is characterized by the presence of malignant glandular epithelial cells. "Thus, this indicates that SASH1 is an independent prognostic factor for lung adenocarcinoma." (PMID 33122723, 2020). "Consistent with above univariate analyses, in multivariate Cox proportional hazard analyses, low SASH1 expression significantly predicts poor survival outcome for patients with NSCLC (p = 0.0092) and lung adenocarcinoma (p = 0.0095) but not for squamous cell carcinoma (p = 0.2815)." (PMID 33122723, 2020).
meningioma (2 papers, 2019 to 2026). A generally slow growing tumor attached to the dura mater. "Hsa-miR-21-5p enhanced proliferation and viability of KT21-MG1 meningioma cells and showed a regulatory effect on IL6R, IL6ST and other predicted target genes TIMP3, PIK3R, RHOB, and SASH1 by interacting with 3'UTRs." (PMID 42196381, 2026).
osteosarcoma (2 papers, 2015 to 2016). A usually aggressive malignant bone-forming mesenchymal neoplasm, predominantly affecting adolescents and young adults. "SASH1 expression was significantly deceased or absent in various cancers including colorectal cancer, melanoma, osteosarcoma, and lung cancer." (PMID 26424902, 2015). "Induction of SASH1 expression reduced cyclin D1 and matrix metalloprotease- (MMP-) 9 expression and increased caspase 3 expression, which suggested that overexpression of SASH1 in human osteosarcoma MG-63 cells might inhibit cell growth, proliferation, and invasion and promote apoptosis." (PMID 26424902, 2015).
adenoma (1 paper, 2006). A neoplasm arising from the epithelium. "SASH1 expression was not reduced in adenomas and locally restricted, low-stage tumours (UICC I)." (PMID 17088907, 2006). "However, SASH1 expression was not significantly deregulated in precancerous adenomas and in earlier stage lesions (UICC I)." (PMID 17088907, 2006). "SASH1 was significantly downregulated in tumour stages UICC II, III and IV, but not in adenomas or UICC stage I cancers." (PMID 17088907, 2006).
alcohol dependence (1 paper, 2022). Physical and psychological dependence on alcohol. "It has also been suggested that genetic variants of SASH1 are associated with other psychiatric disorders and traits, e.g., comorbid major depression, alcohol dependence, and smoking behavior." (PMID 35999196, 2022).
Alzheimer disease (1 paper, 2023). A progressive, neurodegenerative disease characterized by loss of function and death of nerve cells in several areas of the brain leading to loss of cognitive function such as memory and language. "Using the TWAS-hub35, SASH1 showed strong evidence (ENET-P = 7.5 × 10–9) of involvement in the prefrontal cortex tissue and a strong association with “Alzheimer’s Disease (in father)”." (PMID 37848535, 2023).
breast tumour (1 paper, 2016). "After immunohistochemical (IHC) staining of the TMAs with a well-characterised SASH1 antibody, we observed reasonably homogeneous nuclear staining of breast tumour cells, and scored this as negative, weakly, moderately or strongly positive (0, 1, 2 or 3+, respectively)." (PMID 27637080, 2016).
chronic hepatitis B (1 paper, 2024). "In conclusion, our research highlights DENND2A and SASH1 in the immune system during HBV infection and 10M-DEN3SN as the potentially effective drug in the treatment of chronic hepatitis B." (PMID 38240571, 2024).
congenital heart disease (1 paper, 2023). A heart disease that is present at birth. "Additionally, 3 mutation sites (3/31, 9.70%) in SASH1 have been linked to congenital heart disease." (PMID 37543808, 2023).
congenital hypothyroidism (1 paper, 2013). A thyroid hormone deficiency present from birth. "Among them, the reported signals at SOX9, ABO, SASH1, GLIS3 and MIR1179 will need to be confirmed in other studies; but one of them - GLIS3- is a prime candidate, because it is involved in congenital hypothyroidism." (PMID 23408906, 2013).
diabetic nephropathy (1 paper, 2017). "Among these genes and loci, 11p11.2 and SASH1 were previously identified as susceptibility loci for CKD or diabetic nephropathy, respectively." (PMID 28410202, 2017).
ependymal tumor (1 paper, 2014). A group of neoplasms which arise from the ependymal lining of the cerebral ventricles and from the remnants of the central canal of the spinal cord. "Some genes mapping to the long arm of chromosome 6 have previously been reported to be downregulated in ependymal tumors, including SASH1 [a candidate tumor suppressor gene in breast and colon cancer], TCP1 (involved in tubulin function), ADM1 and CDK11 (involved in cell proliferation)." (PMID 24939246, 2014).
generalized lentiginosis (1 paper, 2021). "In contrast, diseases caused by SASH1 mutations are more likely to be confused with generalized lentiginosis." (PMID 34174894, 2021).
hereditary nonpolyposis colorectal cancer (1 paper, 2006). "Interestingly, SASH1 expression was normal in a tumour from a patient diagnosed with hereditary nonpolyposis colorectal cancer (HNPCC) syndrome and MSI-high status (not shown)." (PMID 17088907, 2006).
leukemia (1 paper, 2025). A malignant (clonal) hematologic disorder, involving hematopoietic stem cells and characterized by the presence of primitive or atypical myeloid or lymphoid cells in the bone marrow and the blood. "Interestingly, the SASH1-Sam1 Y652A mutation inhibits the formation of the SASH1-Sam1/EphA8-Sam complex, whereas the leukemia-linked mutation G978D in EphA8-Sam highly reduces the binding affinity for SASH1-Sam1 by interfering with the network of interactions engaging the key G978 residue." (PMID 39942820, 2025).
liver cancer (1 paper, 2020). An epithelial or non-epithelial malignant neoplasm that arises from the liver. "Previous studies have identified a role of SASH1 in inhibiting phosphatidylinositol 3-kinase (PI3K)/protein kinase B (AKT) signaling in thyroid and liver cancer." (PMID 32670859, 2020).
meningococcal meningitis (1 paper, 2019). "This is in SASH1, which has previously been found to have decreased expression during meningococcal meningitis (BioProject PRJNA106047)." (PMID 31092817, 2019).
schizophrenia (1 paper, 2017). A major psychotic disorder characterized by abnormalities in the perception or expression of reality. "GAS2L1 is a susceptibility locus for schizophrenia, and SASH1 gene expression was affected by a history of substance dependence/abuse." (PMID 29321746, 2017).
spinal cord injury (1 paper, 2023). Penetrating and non-penetrating injuries to the spinal cord resulting from traumatic external forces (e.g., WOUNDS, GUNSHOT; WHIPLASH INJURIES; etc.). "This study aimed to evaluate the effects of the depletion of SAM and SH3 domain‐containing protein 1 (SASH1) on functional recovery after spinal cord injury (SCI) and to investigate the possible mechanism of SASH1 knockdown in astrocytes facilitating axonal growth." (PMID 36286186, 2023). "Therefore, in this study, we first depleted the expression of SASH1 in rat SCI to determine whether depletion of SASH1 contributes to the functional recovery after spinal cord injury (SCI) and to investigate the possible mechanism of SASH1 knockdown in astrocytes facilitating axonal growth." (PMID 36286186, 2023).
squamous cell carcinoma (1 paper, 2020). A carcinoma arising from squamous epithelial cells. "SASH1 mRNA expression was evaluated separately in adenocarcinoma and squamous cell carcinoma cohorts." (PMID 33122723, 2020). "SASH1 expression in squamous cell carcinomas did not stratify patients survival." (PMID 33122723, 2020).
tumor (46 papers, 2006 to 2025). "This is further corroborated by our clinical correlation analysis, where SASH1 expression levels were significantly correlated with survival status, gender, and clinical stage, indicating that its loss is closely linked to tumor progression and malignancy." (PMID 41099090, 2025). "Reduced expression of SASH1 is associated with aggressive tumor growth, metastasis formation, and poor patient survival." (PMID 32174800, 2020). "SASH1 expression has been negatively associated with aggressive tumour growth and metastasis formation in different types of cancer, including the breast, colon, and bone." (PMID 26798410, 2016). "The CpG-site falls in an intergenic region, 70 kb upstream of the nearest gene, SASH1, a known tumour suppressor gene previously associated with aggressive tumour growth and metastasis formation in different types of cancer." (PMID 26798410, 2016). "Both of these studies suggested an association of decreased SASH1 expression with tumor progression and metastases." (PMID 26424902, 2015). "SASH1 has been proposed as a tumor suppressor, based on the correlation of the presence of SASH1 mRNA expression with beneficial prognosis in several human cancers and the observation that loss or depletion of SASH1 enhances tumor cell line survival and invasiveness in vitro." (PMID 33122723, 2020). "Although changes to SASH1 expression have been linked with several other diseases, these associations need further investigation to cement the role of SASH1 as a tumor suppressor relevant to cancer prognoses, particularly within the context of apoptosis, cell cycle and proliferation." (PMID 33122723, 2020). "However, SASH1 expression differences were statistically significant for survival status (P = 0.025), gender (P = 0.038), and clinical stage (P = 0.01), suggesting associations with prognosis, gender differences, and tumor progression." (PMID 41099090, 2025). "This discovery not only provides decisive evidence from a clinical cohort supporting the tumor-suppressive role of SASH1 but also highlights its immense potential as an independent prognostic biomarker for HNSCC." (PMID 41099090, 2025). "SASH1, acting as a tumor suppressor and mitochondrial epistasis gene, regulates oxidative stress, cell adhesion, and migration." (PMID 40018519, 2025). "First, gain-of-function and loss-of-function experiments should be conducted on SASH1 in HNSCC cells and animal models using CRISPR/Cas9 gene-editing technology to directly verify its effects on tumor proliferation, invasion, and matrix remodeling." (PMID 41099090, 2025). "SASH1 expression was notably low across the vast majority of the tissue, particularly within the large, dense areas annotated as Fibrotic Stroma and most tumor subregions." (PMID 41099090, 2025). "Subsequently, by using spatial transcriptomics, we provided spatial evidence at the in-situ tissue level, revealing a pattern of spatial exclusion between SASH1 expression and the fibrotic tumor microenvironment." (PMID 41099090, 2025). "Our models demonstrated that EFHD1 and SLC25A18 were significantly associated with the cell cycle (R2 = 0.790), while SASH1 and FAM110B showed a notable association with tumor stemness (R2 = 0.522)." (PMID 40018519, 2025). "On the other hand, DENND2A is known as GEF in the Rab family, and SASH1 is reported in tumor suppression, cellular proliferation, and adhesion (35, –, 37)." (PMID 38240571, 2024). "Deletion of the SASH1 gene in tumor samples significantly correlates with poor patient survival in the TCGA pan-cancer data set." (PMID 37296980, 2023). "SASH1 is a scaffold protein with context-dependent biological functions, including suppression of tumor metastasis, lung development, and pigmentation." (PMID 37296980, 2023). "All subtypes examined showed decreased SASH1 expression in the tumour tissue compared to normal tissue." (PMID 33122723, 2020).
tumor (continued). "Some studies have reported that reduced SASH1 expression will inversely increase the tumor proliferation, invasion, and metastasis." (PMID 32230784, 2020). "The continuous delivery of agomiR‐130b led to a greater tumour weight, whereas the continuous delivery of the SASH1 overexpression plasmids yielded a reduced tumour weight (P < 0.01)." (PMID 30443973, 2019). "All together, these data indicated that miR‐130b promoted the growth of ESCC tumours by suppressing the anti‐oncogene SASH1 in vivo." (PMID 30443973, 2019). "Several studies report that SASH1 is down‐regulated in tumours and that this expression is correlated with tumour grade and prognosis." (PMID 30443973, 2019). "Based on its association with favourable prognosis in multiple human malignancies and adverse effects on cancer cell line viability and invasiveness in vitro, SASH1 has been proposed as a tumour suppressor." (PMID 27637080, 2016). "We reported in previous study that cyclin D1 and MMP-9 expression were decreased, and caspase 3 expression was increased by overexpression of SASH1 in U251 cells, supporting the role of SASH1 as a candidate tumor suppressor." (PMID 26424902, 2015). "This included genes in which upregulation is implicated in cancer (CTDSP2, CASC3, PGF) and those that are thought to be involved in tumor suppression (SASH1, HIPK2)." (PMID 23406646, 2013). "The group of 113 patients was then statistically evaluated by multivariate regression analysis for overall survival using the following factors: age, sex, disease recurrence, pT and nodal status (pN) status, tumour grading, and SASH1 expression." (PMID 17088907, 2006). "Our study focuses on SASH1, a new candidate tumour suppressor gene of the SLY1 family of signal adapter proteins." (PMID 17088907, 2006). "In three cases, SASH1 was already downregulated in the primary tumour, and in two patients, the SASH1 mRNA level of the liver metastasis was significantly lower than that of the matched primary tumour (P<0.01)." (PMID 17088907, 2006). "Statistical analysis revealed that downregulation of SASH1 in the primary tumour correlated with the formation of metachronous, postoperative metastasis, and with the progression of synchronous metastases." (PMID 17088907, 2006). "SASH1 demonstrated a decreasing expression trend from pre-pseudotime tumor cells and myeloid cells." (PMID 40018519, 2025). "Another significant finding of this study reveals the potential extrinsic function of SASH1 at the level of the tumor microenvironment, suggesting it may act as a key molecule regulating tumor-stroma interactions." (PMID 41099090, 2025). "Taken together, SASH1 in tumor cells can be a tumor suppressor for multiple cancers." (PMID 37296980, 2023). "SASH1 plays a role in actin dynamics and regulates cytoskeletal reorganization and integrin-mediated cell adhesion, which likely contributes to its role in suppressing tumor metastasis." (PMID 37296980, 2023). "Sash1 may be involved in tumor suppression; induction of Sash1 appears to be involved in NFκB-dependent apoptotic signaling." (PMID 36235565, 2022). "SASH1 gene may inhibit the invasion and metastasis of tumor cells by inhibiting the expression of MMP-2/9 in A549 cells." (PMID 33134379, 2020). "SASH1 has been regarded as a tumor suppresser in various type of tumors." (PMID 32670859, 2020). "To determine whether SASH1 acts as a tumor suppressor in NSCLC, we next examined whether SASH1 depletion altered the proliferation of a panel of NSCLC cell lines." (PMID 33122723, 2020). "This suggests that increasing SASH1 protein levels in NSCLC may be a strategy to reduced tumour cell proliferation." (PMID 33122723, 2020). "The characteristics of trophoblast cells are similar to those of tumor cells, while upregulated SASH1 could enhance cell death and inhibit the proliferation and invasion of tumor cells." (PMID 33134379, 2020).